AURKA (aurora kinase A)
Diseases named in the same sentence as AURKA in open-access papers (continued):
Sharing a sentence is not in itself a finding about the gene and the disease.
cancer (continued). "AURKA overexpression in HCC is closely linked with cancer progression, influencing several key cellular pathways responsible for tumor proliferation, survival, migration, and invasion." (PMID 39598228, 2024). "In summary, our results show that AURKA overexpression caused by a disruption in the SLR of APA isoforms in favor of the short isoform contributes to cancer-like cell behavior." (PMID 37384380, 2023). "The observed correlation suggests that AURKA overexpression in cancer associates with conditions of increased protein import." (PMID 36797043, 2023). "AURKA has drawn much attention as its dysregulation is critically associated with various cancers, leading to the development of AURKA inhibitors, a new class of anticancer drugs." (PMID 36830089, 2023). "We observed AURKA overexpression in various cancers, including ESCA, and its close association with patients’ OS and disease-free survival (DFS)." (PMID 37965456, 2023). "Among the three human aurora kinases, AURKA has been the family member most consistently associated with cancer." (PMID 36839989, 2023). "Our current and previous studies indicated that Aurora kinase A (AurA), a mitotic regulator that is often aberrantly expressed in human cancers, is preferentially bound to E6-encoded by cancer-causing HPV." (PMID 36715516, 2023). "AURKA overexpression in human cancers is known to be caused by elevated gene copy number, enhanced transcription, or increased protein stability." (PMID 37384380, 2023). "In this study, we initiated our exploration by examining AURKA’s expression, prognostic significance, and associated immune characteristics using a pan-cancer approach based on The Cancer Genome Atlas (TCGA) database." (PMID 37965456, 2023). "Because AURKA overexpression is a common feature of cancer, we interrogated the mutated cell lines for changes in cancer-relevant behavior." (PMID 37384380, 2023). "Overexpression of Aurora A (AURKA) is frequently associated with the self-renewal and tumorigenicity of various cancers." (PMID 36937887, 2023). "To summarize, inclusions of exon II and of exon III seem to be linked to cancer, for example as they render AURKA mRNA responsive to growth factors signalling." (PMID 36067794, 2022). "Persistent association of high expression of AURKA with cancer progression, poor prognosis and drug resistance has been reported to such an extent that AURKA represents a distinguished target in the development of anti-cancer drugs." (PMID 36067794, 2022). "Overexpression and amplification of the Aurora kinase genes, particularly AURKA, have been documented for many types of neoplasia, with some data evidencing association with clinical parameters, survival, and cancer risk." (PMID 36175852, 2022). "In another study, immunohistochemistry showed the overexpression of AURKA in EC tissues compared with control endometrial tissue, and AURKA overexpression was associated with the cancer grade." (PMID 36232772, 2022). "Because SNAI1, FN1, and MMP9 play a key role in inducing EMT-associated cancer plasticity, chemoresistance, and metastasis, we aimed to define the pivotal role of AURKA in mediating TGF-β-induced expression of SNAI1, FN1, and MMP9 genes." (PMID 33674749, 2021). "Many of the substrates regulated by AURKA coordinate with AURKA to control mitotic progression, and aberrant expression of AURKA in a variety of human cancers has been linked with mitotic defects." (PMID 33451333, 2021). "Next, we investigated the extent to which TNBC-M14 and TNBC-M25 chemoresistant phenotype were linked to TGF-β/AURKA axis-induced cancer plasticity." (PMID 33674749, 2021). "The AURKA gene encodes a protein kinase involved in cell cycle regulation and plays an oncogenic role in many cancers." (PMID 34337875, 2021).
cancer (continued). "SOCS2-AS1 exerted its tumor-suppressive activity through interaction with and promotion of AURKA ubiquitin degradation, thereby reducing the levels of AURKA protein and its target mRNAs—including those mRNAs directly associated with cancer cell growth." (PMID 33824269, 2021). "The mutation data for all 13 common cancers indicated that the AURKA gene had a variety of mutations in various cancer samples, and the percentage of SNP mutations was more than other types." (PMID 34337875, 2021). "One mechanism involves AURKA overexpression after mutation of a tumor suppressor, leading to oncogene addiction in cancer cells." (PMID 34050264, 2021). "The further evaluation of IGF2BP1’s role in modulating the expression of such effectors like AURKA will unravel novel avenues to pursue the inhibition of IGF2BP1-mRNA association in combinatorial treatment strategies to improve cancer patient outcome." (PMID 33829040, 2021). "The underlying mechanisms for AURKA upregulation in cancer include gene amplification, gene mutation, microRNA regulation, transcriptional or posttranscriptional modification, and others." (PMID 33451333, 2021). "Increased expression of AURKA is observed in prevalent cancers and associated with poor prognostic and the development of drug resistance." (PMID 34337875, 2021). "This case–control study was performed to analyze the relationship between AURKA gene SNPs and CNS tumor risk in 191 patients and 248 cancer-free controls." (PMID 35201446, 2021). "Overexpression of AURKA is detected in a wide spectrum of cancers, and it is associated with poor clinical outcomes, rendering it a highly important therapeutic target." (PMID 34359608, 2021). "By analyzed targeted next-generation sequencing panel captured mutations in coding regions, we found the correlation between the expression of AURKA and mutations in 450 cancer-related genes in HCC samples." (PMID 34337035, 2021). "Further investigation on AURKA as a drug target in cancers where other SWI/SNF components are frequently mutated is warranted." (PMID 34050264, 2021). "Given the importance of these three AURKA gene SNPs to altered cancer risk, and the correlation of these AURKA gene polymorphisms with CNS tumors has not been studied." (PMID 35201446, 2021). "Meanwhile, other recent studies showed that AURKA gene polymorphisms have a complete connection with increasing the risk of some cancers like liver and breast." (PMID 34337875, 2021). "Other AURKA SNPs such as rs2064863 and rs6024836 have been found to be related to cancer susceptibility." (PMID 35201446, 2021). "The Aurora kinase A (AURKA) gene encodes a key regulator of mitosis and is frequently amplified and/or overexpressed in cancer." (PMID 33916038, 2021). "The association between the AURKA rs2273535 T>A polymorphism and cancer risk has been investigated, but the results remain inconsistent." (PMID 32733797, 2020). "Aurora kinase A (encoded by AURKA) is aberrantly expressed in many cancers, including GBM, making it a plausible candidate for a targeted GBM therapy." (PMID 33585252, 2020). "Pooled analysis indicated that the AURKA rs2273535 T>A polymorphism increased the overall risk of cancer (homozygous: OR = 1.17, 95% CI = 1.04-1.33; recessive: OR = 1.15, 95% CI = 1.05-1.25; allele: OR = 1.07, 95% CI = 1.02-1.13)." (PMID 32733797, 2020). "AURKA, a cell cycle-regulated kinase, is associated with malignant transformation and progression in many cancer types." (PMID 32851091, 2020). "High expression of AURKA has previously been detected in different cancer types as well, which is implicated with the regulation of cell cycle and division." (PMID 31886176, 2019). "In line with this, a single-nucleotide polymorphism (SNP) near the AURKA gene was previously associated with cancer risk in BRCA2 mutation carriers." (PMID 30177840, 2019). "A number of polymorphisms in the AURKA have also been reported to exhibit an effect on the risk of cancer onset." (PMID 31521144, 2019).
cancer (continued). "It is worth mentioning that studies also have found that overexpression or expansion of AURKA is associated with poor prognosis in a variety of cancer patients and inhibition of AURKA expression can trigger tumor cell death." (PMID 31636670, 2019). "Previous studies have demonstrated that polymorphisms in the AURKA gene are associated with various types of cancer." (PMID 29678897, 2018). "Gain of 20q and/or AURKA overexpression is associated with a poor prognosis in many cancer types including CRC12–17." (PMID 29760449, 2018). "AURKA, also known as Aurora Kinase A, encodes a centrosome-related serine/threonine kinase and is frequently amplified and overexpressed in many human cancers, particularly advanced OSCC." (PMID 28152093, 2017). "AURKA, which encodes a centrosome-related serine/threonine kinase, is frequently amplified and overexpressed in many human cancers, particularly advanced OSCC." (PMID 28152093, 2017). "Some of these same mitotic genes are being investigated as emerging cancer therapy targets including ones (i.e., AURKA and PLK1) that are implicated in cancers with “poorer prognosis”." (PMID 28817068, 2017). "If cancer stem cells express Aurora Kinase A at the same elevated rate as the remainder of the cancer cell population, they should remain susceptible to TCR transfer immunotherapy." (PMID 27271876, 2016). "The AURKA mutation (Phe31Ile) is determined to confer an increased risk for multiple types of cancer in several studies." (PMID 26102504, 2015). "In agreement with our data, other pathway components and Ran-associated genes are also overexpressed in cancer: Aurora kinase A, TPX2, and HSET." (PMID 26683658, 2015). "Results suggest a nuanced role of AURKA signaling in different pathogenic conditions and inform the clinical use of AURKA inhibitors in cancer patients with comorbidities." (PMID 26528438, 2015). "Our results indicate that AURKA rs2273535 is a candidate gene polymorphism, and rs1047972 polymorphism is a protective factor for BC cancer risk." (PMID 25253995, 2014). "For example, the TPX2 gene encodes an Aurora kinase A-stimulated microtubule regulating molecule that when over-expressed in cancer is associated with tumorigenesis." (PMID 23785665, 2013). "Expression of AURKA distinguished ER+/HER2- low-risk luminal A like carcinomas from ER+/HER2- high-risk luminal B like carcinomas." (PMID 23186136, 2012). "Previous data has pointed out that AURKA over-expression is associated with the carcinogenesis and/or drug resistance in many human malignant tumors." (PMID 21718475, 2011). "Finally, we demonstrate that the cancer-associated polymorphism F31I enhances AURKA activation and ATP production on ATP synthase-enriched subdomains." (PMID 42227232, 2026). "Notably, BRCA1, BRCA2, and AURKA played significant regulatory roles within the gene expression network and are strongly implicated in cancer onset and progression." (PMID 40666234, 2025). "Hence, AURKA overexpression has been implicated in tumorigenesis and associated with poor overall survival in patients with various cancers." (PMID 39789853, 2025). "Based on our previous finding that hsa-let-7a miRNA and APA of AURKA mRNA can control AURKA protein levels, we explored the extent to which such association may provide a general mechanism for AURKA overexpression in cancer." (PMID 39527514, 2024). "Furthermore, high levels of AURKA expression are associated with chemotherapy resistance in certain cancers." (PMID 39834933, 2024).
cancer (continued). "Because of the significant association between high AURKA expression and cancer progression, poor prognosis, and drug resistance, AURKA is a preferred target for anti-cancer strategies, especially the use of small molecule kinase inhibitors and targeted proteolytic tools." (PMID 39527514, 2024). "Further, AURKA overexpression promoted cell cycle progression in the presence of DNA damage or chromosome segregation abnormalities, leading to genomic and chromosomal instability, a hallmark of malignant tumors." (PMID 39585848, 2024). "AURKA has been implicated in cancer-directed therapy resistance in multiple studies." (PMID 39199578, 2024). "We then examined the extent to which APA is linked to AURKA expression and how it may be associated with hsa-let-7a in mediating AURKA expression across cancers." (PMID 39527514, 2024). "We point to a heterogeneous landscape of how hsa-let-7a might be implicated in the regulation of AURKA expression in cancer." (PMID 39527514, 2024). "Given the key role of post-transcriptional control in cancer, analyses of isoform-specific expression may reveal mechanisms converging on mRNA that underlie dysregulated AURKA expression and that the studies carried out to date have overlooked." (PMID 39527514, 2024). "AURKA overexpression in numerous cancers is strongly associated with poor prognosis and survival." (PMID 39334449, 2024). "AURKA is also known to promote uncontrolled cellular proliferation, a hallmark of cancer." (PMID 39598228, 2024). "Among the 12 cuproptosis-associated ferroptosis genes, AURKA belongs to the aurora family of kinases and plays a crucial role in mitosis, spindle assembly, and cytoplasmic division of cells, and is a driver of several cancers." (PMID 38673957, 2024). "High expression of AURKA is strongly associated with cancer progression, drug resistance, and poor prognosis, justifying why oncogenic AURKA represents a renowned target of anticancer drugs, and making evident that oncogenic roles of AURKA are prompted by its highly sustained levels of expression." (PMID 37384380, 2023). "The abnormal expression of AURKA has been associated with a number of cancers." (PMID 36703644, 2023). "Abnormally expressed AURKA is linked to cancer biology in recent years." (PMID 35166647, 2022). "AURKA, a cell cycle kinase, is associated with many cancer types." (PMID 35520289, 2022). "In summary, the mitotic inhibitory effects of curcumin on cancer cells may be closely associated with the down-regulation of AURKA." (PMID 35699421, 2022). "In this review, we will focus on research progress associated with AURKA in cancer." (PMID 33451333, 2021). "Although many AURKA polymorphisms were reported in previous studies, just some of which might indicate profound relation between these mutations and cancers." (PMID 34337875, 2021). "Having a role in cell cycle, AURKA polymorphisms have a significant effect on cancers." (PMID 34337875, 2021). "Among the three aurora kinase family members, AURKA has been the most extensively studied, as it plays a central role in mitotic regulation and because its expression is highly associated with many types of cancer." (PMID 34050264, 2021). "In general, all these negative regulators of AURKA function as tumor suppressors, and their loss or inactivation may play an important role in AURKA-mediated cancer development." (PMID 34050264, 2021). "In conclusion, our pan‐cancer outcomes suggested that some new unknown mutations in AURKA could be discovered in many types of cancers." (PMID 34337875, 2021). "Furthermore, the association of AURKA with cell proliferation, epithelial-mesenchymal transition, metastasis, chemoresistance, and self-renewal capacity of cancer stem cells have been previously reviewed." (PMID 32978717, 2021). "Given its central role in mitosis, the AURKA/PLK1 axis is associated with many types of cancers." (PMID 34500603, 2021). "For the past few years, many studies have linked AURKA to human cancers." (PMID 35201446, 2021).
cancer (continued). "This study shows that stathmin-mediated disruption of microtubule dynamics is critical to induce synthetic lethality in RB1-deficient cancer and suggests that upstream factors regulating microtubule dynamics, such as AURKA, can be potential therapeutic targets in RB1-deficient cancer." (PMID 33037191, 2020). "AURKA inhibition-associated genomic instability might be synthetically lethal in cancers with defects in certain DNA repair genes." (PMID 33054831, 2020). "Studies have shown that AURKA is involved in multiple mechanisms-associated with cancer initiation." (PMID 33245732, 2020). "A number of recent studies demonstrated that AURKA is frequently overexpressed in a wide spectrum of cancers, and its overexpression is associated with poor clinical outcomes in cancer patients, rendering it a highly important cancer target." (PMID 33037191, 2020). "Studies in recent years have shown that AURKA SNPs were closely related to cancer risk." (PMID 31636670, 2019). "Several studies have demonstrated that AURKA SNPs were associated with the risk of cancer." (PMID 29678897, 2018). "Overexpressed AURKA (located on the 20q amplicon) is also strongly associated with cancer." (PMID 29899121, 2018). "In addition, several studies confirmed that AURKA polymorphisms were associated with the risk of several human cancers." (PMID 29678897, 2018). "AURKA (aurora kinase A) has been identified as an oncogene in cancer development; however, its potential role and underlying mechanisms in the progression of BC remain unknown." (PMID 30547784, 2018). "AURKA has been reported to be overexpressed in several human malignancies and encodes a serine/threonine kinase that is involved in the processes of proliferation, survival, invasion, and stemness in multiple types of cancer." (PMID 29678897, 2018). "We speculate that the other alterations required for cancer cells to survive loss of SMARCA4 may also contribute to sensitivity to AURKA inhibitors." (PMID 28102363, 2017). "Notably, AURKA overexpression in cancer cells has also been implicated in activating a plethora of prosurvival oncogenic pathways including β‐catenin, NF‐κB, and AKT." (PMID 28417568, 2017). "Having these findings in mind, we expect that the two functional polymorphisms (Ile31Phe and Val57Ile) in the AURKA gene may act as genetic modifiers in individual susceptibility to human cancer." (PMID 28903390, 2017). "Previous studies have demonstrated that AURKA 91A (Ile31) is a low-penetrance tumor susceptibility allele, and individuals homozygous or heterozygous for this allele tend to exhibit an increased risk of several human cancers." (PMID 28152093, 2017). "Therefore, the functional polymorphisms of the AURKA gene need to be considered as a possible modification factor for cancer treatments using such inhibitors and for subsequent clinical trials." (PMID 28903390, 2017). "Previous studies have identified several mutations of AURKA in cancer, such as F31I and V57I54." (PMID 26782714, 2016). "In particular, AURKA has been extensively investigated for its implication in different neoplasms and it has been identified as a low penetrance tumor-susceptibility-gene in human cancer." (PMID 27209210, 2016). "Several studies demonstrate that Aurora kinases, particularly AURKA, are over-expressed in various tumors, highly associated with the abnormal growth of cancer cells, and may serve as an additional biomarker for AML." (PMID 27863392, 2016). "Aurora Kinase A is a cancer-associated protein normally involved in the regulation of mitosis." (PMID 27271876, 2016). "Notably, AURKA overexpression has been significantly associated with more advanced stages of cancer and poor prognosis." (PMID 25593196, 2015).